EPPIN-WFDC6 (EPPIN-WFDC6 readthrough)
Description:
Serine protease inhibitor that plays an essential role in male reproduction and fertility. Modulates the hydrolysis of SEMG1 by KLK3/PSA (a serine protease), provides antimicrobial protection for spermatozoa in the ejaculate coagulum, and binds SEMG1 thereby inhibiting sperm motility.
Synonyms: SPINLW1-WFDC6
Gene: Protein-coding gene on chromosome 20 (45,534,196 to 45,547,662, reverse strand). Ensembl gene ENSG00000249139.
Subcellular location: Secreted (Isoform 1); Cell surface; Secreted
Pathways (Reactome):
Immune System: Antimicrobial peptides
Gene Ontology:
Molecular function: protein binding; peptidase inhibitor activity; serine-type endopeptidase inhibitor activity
Biological process: defense response to bacterium; negative regulation of calcium ion import; negative regulation of flagellated sperm motility; negative regulation of peptidase activity
Cellular component: cell surface; extracellular region; protein-containing complex; sperm plasma membrane; acrosomal vesicle; cytoplasm; sperm flagellum; sperm head
Genetic constraint (gnomAD): Loss-of-function variants: 18 observed, 20.07 expected, observed/expected ratio (o/e) 0.9, 90% interval 0.62 to 1.33. The upper end of that interval is the gene's LOEUF score, 1.33, which puts it in group 5 of 6, group 1 being the genes least tolerant of losing a copy. Missense variants: 164 observed, 177.98 expected, observed/expected ratio (o/e) 0.92, 90% interval 0.81 to 1.05. Synonymous variants: 57 observed, 64.55 expected, observed/expected ratio (o/e) 0.88, 90% interval 0.71 to 1.1.